YTHDF1 (YTH N6-methyladenosine RNA binding protein F1)
Diseases named in the same sentence as YTHDF1 in open-access papers (continued):
Sharing a sentence is not in itself a finding about the gene and the disease.
adenocarcinoma (2 papers, 2021 to 2022). A common cancer characterized by the presence of malignant glandular cells. "Representative figures of immunohistochemistry in adenocarcinoma show that high YTHDF1 or YTHDF2 cases are associated with low CD4, CD8 and high FOXP3 expression in both PD-1 inhibitor treatment and non-treatment groups." (PMID 36479088, 2022). "In the adenocarcinoma group receiving PD-1/PD-L1 inhibitor treatment, the immunohistochemical expression of YTHDF1 was significantly negatively associated with CD4 expression." (PMID 36479088, 2022). "The YTHDF1 or YTHDF2 mRNA expression was significantly negatively associated with CD4, CD8, and FOXP3 mRNA expression in adenocarcinoma." (PMID 36479088, 2022). "YTHDF1 knockdown abolishes reactive oxygen species production generated by hydrogen peroxide in A549 adenocarcinoma." (PMID 33616673, 2021). "YTHDF1 has an immune hot profile in both cell types, whereas YTHDF2 is only seen in adenocarcinoma." (PMID 36479088, 2022). "In the adenocarcinoma group not receiving PD-1/PD-L1 inhibitor, the cutoff values of YTHDF1 and YTHDF2 were 60 and 75, respectively." (PMID 36479088, 2022).
neurological diseases (2 papers, 2022 to 2024). "Further exploration of the interactions between Wtap, Ythdf1, and other m6A-related molecules, as well as their roles in other neurological disorders, will contribute to a more comprehensive comprehension of the biological significance of m6A modification." (PMID 39110292, 2024). "Several studies have shown that YTHDF1 is a methyl-binding enzyme that mediates the Wnt/β-catenin signaling pathway and may be an important pathway for its involvement in neurodevelopment and neurological diseases." (PMID 35356237, 2022).
immune diseases (1 paper, 2024). "Moreover, reduced expression levels of DNMT3A, METTL3, and YTHDF1 were associated with immune diseases or immune signalling pathways." (PMID 39485681, 2024).
YTHDF1 also shares sentences with these, for which no sentence is quoted: schizophrenia (6 papers); otitis media (5); stomach adenocarcinoma (4); 22q11.2 deletion syndrome (3); breast invasive carcinoma (3); Hearing impairment (3); prostate adenocarcinoma (3); sarcoma (3); uterine corpus endometrial carcinoma (3); adrenocortical carcinoma (2); bladder urothelial carcinoma (2); cervical squamous cell carcinoma (2); chronic myeloid leukaemia (2); cutaneous melanoma (2); diabetes (2); idiopathic pulmonary fibrosis (2); ischemia (2); Kidney chromophobe (2); lung (2); lymphoid neoplasm (2); paraganglioma (2); pheochromocytoma (2); serous ovarian cancer (2); adenoma (1); Allergy (1); aortic arch defects (1); benign breast neoplasm (1); brain injury (1); catalepsy (1); chromosomal disorder (1).
A further 46 diseases each share a sentence with YTHDF1 in 1 paper.